COL4A5 (collagen type IV alpha 5 chain)
Diseases named in the same sentence as COL4A5 in open-access papers (continued):
Sharing a sentence is not in itself a finding about the gene and the disease.
Alport syndrome (continued). "Previous studies have identified that autosomal dominant mutations of Col4A3, Col4A4 or Col4A5 are associated with thin basement membrane nephropathy (TBMN), Alport syndrome and other hereditary kidney diseases." (PMID 37323683, 2023). "Alport syndrome (AS) is a rare disease characterized by defective glomerular basement membranes, caused by mutations in COL4A3, COL4A4, and COL4A5, which synthesize collagen type IV." (PMID 36936689, 2023). "Alport syndrome (AS) is caused by mutations in COL4A3, COL4A4 or COL4A5 genes, mainly pathophysicalological alterations affect the kidney, but the pathophysiology of AS is still not fully understood." (PMID 36968823, 2023). "Alport syndrome (AS) is a rare genetic disease of the glomerular basement membrane (GBM) caused by mutations in the COL4A3, COL4A4, and COL4A5 genes, with a prevalence ranging from 1 in 5,000 to 1 in 53,000 individuals in different populations." (PMID 36714647, 2022). "Alport syndrome is a hereditary kidney disease caused by mutations in the three genes encoding for collagen IV: COL4A3, COL4A4, and COL4A5." (PMID 36292778, 2022). "Alport syndrome is a hereditary disorder characterized by renal impairment, hearing loss, and ocular symptoms and is caused by COL4A3, COL4A4, and COL4A5 mutations." (PMID 36045115, 2022). "One such condition is Alport syndrome, which is caused by variants in COL4A3, COL4A4 or COL4A5 in humans." (PMID 35716957, 2022). "Alport syndrome is inherited as an X-linked (XL), autosomal recessive (AR), or autosomal dominant (AD) disease, where pathogenic COL4A3 – COL4A5 variants affect the basement membrane collagen IV α3α4α5 network." (PMID 35602506, 2022). "Recent advances in genetic analysis have enabled comprehensive and efficient screening of multiple genes including COL4A3, COL4A4, and COL4A5 for patients suspected as having Alport syndrome." (PMID 35211492, 2022). "Alport syndrome is a genetically heterogenous Type IV collagenopathy linked to the COL4A3, COL4A4, and COL4A5 genes." (PMID 35760791, 2022). "The members of the extracellular matrix structural constituent, COL4A3, COL4A4 and COL4A5, have been reported to be consistent with digenic inheritance and, together, lead to the occurrence of Alport syndrome." (PMID 35804365, 2022). "Alport syndrome results from a myriad of variants in the COL4A3, COL4A4, or COL4A5 genes that encode type IV (basement membrane) collagens." (PMID 35223933, 2022). "Many more variants have been reported for COL4A5 than for COL4A3 and COL4A4 because genetic testing has been performed more often for individuals suspected of having X-linked Alport syndrome." (PMID 35602506, 2022). "Of the 17 monogenic disorders detected in our study, Alport syndrome due to COL4A5/COL4A3 accounted for one third of all genetic diagnoses." (PMID 34215756, 2021). "Conversely, 45% of glomeruli exhibited mild injury (score 1) in metformin-treated Col4a5 G5X Alport syndrome mice." (PMID 33782421, 2021). "Alport syndrome (AS) is an inherited renal disease caused by variants in COL4A3, COL4A4, or COL4A5 gene." (PMID 34209341, 2021). "In 677 patients with a priori clinical diagnosis of GN, pathogenic variants in COL4A5, COL4A3 or COL4A4 were detected confirming the diagnosis of Alport syndrome or TBMN." (PMID 36939782, 2021). "Alport syndrome is a genetic and hereditary disease, caused by mutations in the type IV collagen genes COL4A3, COL4A4 and COL4A5, that affects the glomerular basement membrane of the kidney." (PMID 34681722, 2021). "To determine the molecular effect of metformin and losartan on glomeruli in Col4a5 G5X Alport syndrome mice, we assessed the global mRNA expression profile in glomeruli of WT and Alport syndrome mice treated with vehicle, metformin, or losartan for 6 weeks." (PMID 33782421, 2021). "Alport syndrome (AS), which is a rare hereditary disease caused by mutations of genes including COL4A3, COL4A4 and COL4A5, has a wide spectrum of phenotypes." (PMID 34774011, 2021).
Alport syndrome (continued). "Mutations of COL4A5 on the X chromosome, as well as mutations of COL4A3 and COL4A4 on chromosome 2, can cause both Alport Syndrome and FIgAN." (PMID 34717572, 2021). "High-throughput next-generation sequencing (NGS) technology can improve the diagnosis of Alport syndrome by providing molecular confirmation of COL4A3, COL4A4, or COL4A5 mutations." (PMID 34238373, 2021). "Up to now, most reports on Alport syndrome describe patients with XLAS: age at stage 5 chronic kidney disease (CKD 5) strongly correlates with COL4A5 genotype in males with XLAS." (PMID 33772369, 2021). "Consistent with reduced fibrosis, the expression levels of fibrotic genes Mmp9/12, α-Sma, and Tgf-β were lower in kidney tissues of metformin- or losartan-treated Col4a5 G5X Alport syndrome mice." (PMID 33782421, 2021). "Intraglomerular PCNA-positive and periglomerular interstitial α-SMA-positive cells were decreased in metformin or losartan-treated Col4a5 G5X Alport syndrome mice." (PMID 33782421, 2021). "Alport syndrome (AS) is a rare monogenic hereditary disorder caused by mutations in any of the type IV collagen genes COL4A3, COL4A4 (2q36.3 both) and COL4A5 (Xq22.3)." (PMID 34681722, 2021). "Severe glomerular injury (score 4), assessed by PAS staining, was detected in more glomeruli (50%) in untreated Col4a5 G5X Alport syndrome mice (vehicle group) compared respectively with 25% and 15% in losartan- or metformin-treated Alport syndrome mice." (PMID 33782421, 2021). "The transcriptome analyses of kidney and of glomeruli were performed on 16-week-old and 12-week-old Col4a5 G5X Alport syndrome mice, respectively." (PMID 33782421, 2021). "We corrected the diagnosis of four cases of Alport syndrome (COL4A5, n = 1), Lowe syndrome (OCRL, n = 2) and Dent disease (CLCN5, n = 1)." (PMID 36939782, 2021). "To determine the molecular effects of metformin and losartan on Alport syndrome, we assessed the global mRNA expression profile in kidney tissues of WT and Col4a5 G5X Alport syndrome mice treated with vehicle, metformin, or losartan for 10 weeks." (PMID 33782421, 2021). "To compare the effect on glomerular disease, we treated Col4a5 G5X Alport syndrome mice with metformin or losartan, an angiotensin II receptor blocker, as a positive control therapy." (PMID 33782421, 2021). "We treated C57BL/6 background Col4a5 G5X Alport syndrome mice with losartan or metformin via drinking water from 6 weeks old and monitored their survival, as presented in the schematic diagram of treatment." (PMID 33782421, 2021). "Approximately 80% of Alport syndrome patients are X-linked (XLAS) (OMIM # 301050) and because of mutations in the COL4A5 gene (located at position Xq22.3, OMIM 301050, RefSeq Z37153, HGNC 2207; NCBI reference sequence NM_000495.4)." (PMID 32117450, 2020). "Mutations in COL4A5, COL4A3, and COL4A4, the three Alport syndrome genes, have been reported in patients presenting as FSGS." (PMID 31049720, 2020). "Their maintenance, regeneration and remodeling have been extensively studied in normal kidney physiology as well as renal diseases, such as X-linked and autosomal recessive Alport syndrome carrying genetic mutations in COL4A3, COL4A4 or COL4A5 gene." (PMID 32210336, 2020). "Alport syndrome is caused by mutations in the genes COL4A3, COL4A4 or COL4A5 and is characterised by progressive glomerular disease, sensorineural hearing loss and ocular defects." (PMID 31044288, 2020). "Patient 2 had a relatively mild case of Alport syndrome, even though he had a COL4A5 transcript that skipped exon 29 (151 bp), which also resulted in a frameshift." (PMID 32543079, 2020). "Alport syndrome is an inherited renal disease caused by mutations in COL4A3, COL4A4, or COL4A5 genes." (PMID 30883042, 2019). "Mutational Analysis of Alport syndrome genes (COL4A3, COL4A4 and COL4A5) by Beijing Genomics Institute revealed the mutation in COL4A5 (c.1351 T > C, p.Cys451Arg, hemizygous, missense mutation) encoding α5 of type IV collagen." (PMID 31337345, 2019).
Alport syndrome (continued). "Alport syndrome is caused by mutations in the COL4A3 (OMIM, # 120070), COL4A4 (OMIM, # 120131), or COL4A5 (OMIM, # 303630) genes encoding collagen IVα3, α4, and α5 chains." (PMID 30883042, 2019). "Alport Syndrome (AS) is a clinically and genetically heterogeneous, progressive nephropathy caused by mutations in COL4A3, COL4A4, and COL4A5, which encode type IV collagen (Gubler, 2008; Hudson, Tryggvason, Sundaramoorthy, & Neilson, 2003)." (PMID 30968591, 2019). "The first patient was found to have a heterozygous, de novo, pathogenic variant in COL4A5 (c.141+1G>A, IVS2+1G>A), which is associated with Alport syndrome." (PMID 30002862, 2018). "The patient was found to have a heterozygous, de novo, pathogenic variant in COL4A5 (c.141+1G>A, IVS2+1G>A), which is associated with Alport syndrome." (PMID 30002862, 2018). "A much more severe and progressive glomerulopathy, which also presents with MH since childhood is Alport syndrome, caused by either mutations in the COL4A3/A4 genes or mutations in the X-linked COL4A5 gene." (PMID 29764427, 2018). "Alport syndrome (AS) is a clinically and genetically heterogeneous, progressive nephropathy caused by mutations in COL4A3, COL4A4, and COL4A5, which encode type IV collagen." (PMID 28542346, 2017). "Alport syndrome (AS) is an inherited progressive renal disease caused by mutations in COL4A3, COL4A4, and COL4A5 genes." (PMID 28570636, 2017). "Clinical features were compared between individuals with autosomal recessive Alport syndrome caused by COL4A3 or COL4A4 pathogenic mutations and those with X-linked Alport syndrome and COL4A5 mutations." (PMID 27627812, 2016). "This study confirmed that COL4A5, and COL4A3 and COL4A4 mutations in Alport syndrome all resulted in end-stage renal failure at the same age." (PMID 27627812, 2016). "The clinical features in Alport syndrome are explained because the COL4A5 and COL4A3/COL4A4 genes code for the collagen IV α5 chain, α3 and α4 chains which form a heterotrimer in the basement membranes of the glomerulus, cochlea and eye." (PMID 27627812, 2016). "Mutations in the COL4A5 and COL4A6 genes which compromise the production of α5(IV)α5(IV)α6(IV) heterotrimers, result in thinning of the ILM and nerve fiber layer in Alport’s syndrome." (PMID 26230410, 2015). "A hemizygous COL4A5 gene missense mutation (c.1769A->C, p.K590T, MIM# 301050) was detected in patient P2 with Alport Syndrome." (PMID 26274329, 2015). "About 80% of those with Alport syndrome have the X-linked form of the disease (XLAS), which is caused by mutations in COL4A5, the gene encoding the α5 chain of type IV collagen [α5(IV)]." (PMID 17912554, 2009). "The Alport syndrome diffuse leiomyomatosis complex is a contiguous gene syndrome resulting from deletions involving the adjacent COL4A5 and COL4A6 genes on the X chromosome." (PMID 17912554, 2009). "Some genes that can mimic ADPKD, such as COL4A3, COL4A4, and COL4A5 associated with Alport syndrome, were not standardly included as part of the analyses for individuals in these studies." (PMID 41509997, 2026). "In a similar vein, an unusual case of X-linked Alport syndrome mimicking nephrotic syndrome has been reported, where a patient presented with FSGS findings on kidney biopsy, attributed to a likely pathogenic variant in COL4A5." (PMID 41562995, 2025). "Renal damage is the most life-threatening symptom of X-linked Alport syndrome (XLAS), an inherited disease caused by X-linked COL4A5 gene mutations, which cause more than 80% of all Alport syndrome cases (the remaining cases are caused by COL4A3/COL4A4 gene mutations)." (PMID 40075271, 2025). "Additionally, it occurred alongside the pathogenic COL4A5:c.3721G>A variant; however, current recommendations omit the use of the benign-supporting BP2 criterion for Alport syndrome." (PMID 40004525, 2025).
Alport syndrome (continued). "First, this patient had heterozygous variants in COL4A4 and not COL4A5, which is known to be associated with a worse prognosis, especially in males with X-linked Alport syndrome." (PMID 41299396, 2025). "Of 91,000 pregnant people screened by a commercial laboratory, the observed carrier frequency for a P/LP variant was one in 279 for COL4A3, one in 332 for COL4A4, and one in 3055 for COL4A5, giving an overall carrier rate of one in 144 for any one of the Alport syndrome genes." (PMID 40317772, 2025). "Treatment with the chemical chaperone 4-phenylbutyric acid partially restored GBM abnormalities in mild Alport syndrome organoids, whereas an exon-skipping strategy using antisense oligonucleotides restored expression of the C-terminal region of COL4A5 in vitro." (PMID 41302105, 2025). "In three families, variants COL4A5:c.781-2A>G (F048), c.3604+1G>A (F008), and c.4822−16_4822−12del (F006) were assumed to be de novo, and there was no family history of Alport syndrome." (PMID 40004525, 2025). "Alport syndrome is a genetic condition characterized by kidney disease, loss of hearing, and eye abnormalities, due to a mutation in the genes encoding alpha-3, alpha-4, and alpha-5 of type IV collagen (COL4A3, COL4A4, COL4A5) or collagen 4 α345 network." (PMID 41299396, 2025). "Alport Syndrome was the most frequent disorder, with COL4A3 and COL4A5 mutations predominating." (PMID 41288877, 2025). "While maternal carrier status for an X‐linked Alport syndrome gene variant (COL4A5) was disclosed, P/LP variants in COL4A3 or COL4A4 were not reported unless both partners had at least one variant." (PMID 40317772, 2025). "Examples include large deletions encompassing TSC2 and PKD1, resulting in a combined phenotype of tuberous sclerosis complex and autosomal dominant polycystic kidney disease, as well as deletions involving COL4A5 and COL4A6, which cause Alport syndrome with diffuse leiomyomatosis." (PMID 41303235, 2025). "All patients clinically diagnosed with Alport syndrome also exhibited extrarenal manifestations, including sensorineural hearing loss, consistent with syndromic features of AS and supporting the pathogenic relevance of identified COL4A3 and COL4A5 variants." (PMID 41288877, 2025). "Alport syndrome (AS), also known as hereditary nephritis, is a genetically and phenotypically heterogeneous disease caused by mutations in genes encoding type IV collagen, specifically the alpha-3, alpha-4, and alpha-5 chains (COL4A3, COL4A4, COL4A5)." (PMID 39981328, 2025). "Following a genetic test, the results may indicate a genetic variant in one of the Alport syndrome genes (COL4A3, COL4A4, or COL4A5)." (PMID 38745975, 2024). "Alport syndrome (AS) is a hereditary kidney disease caused by pathogenic variants in COL4A3 and COL4A4 genes with autosomal recessive or autosomal dominant transmission or in the COL4A5 gene with X-linked inheritance." (PMID 36982595, 2023). "For example, in two children with CKD (case 36, 44) in whom etiology was unknown, diagnosis of Alport syndrome was made based on detection of homozygous pathogenic variant in COL4A4 and COL4A5 genes." (PMID 37464296, 2023). "Chronic damage may lead to abnormal vascular permeability with leakage of serum proteins into the cystic fluid, similar to what occurs in Alport syndrome, where the genetic inactivation of COL4A5 in glomerular vessels leads to increased proteinuria." (PMID 37627098, 2023). "Alport syndrome exhibits key clinical features such as hematuria, proteinuria, and a progressive decline in kidney function, attributed to genetic mutations in the COL4A3, COL4A4, and COL4A5 genes." (PMID 38235430, 2023). "Increasingly, COL4A5 variants affecting non-canonical splice sites, up to 11 nucleotides from the intron-exon boundary, are identified in individuals with X-linked Alport syndrome." (PMID 33854215, 2021). "Losartan or metformin extended the lifespan of Col4a5 G5X Alport syndrome mice." (PMID 33782421, 2021).
Alport syndrome (continued). "Because metformin attenuated the proteinuria, inflammation and fibrosis in Col4a5 G5X Alport syndrome mice, we investigated whether metformin ameliorates the onset of ESKD." (PMID 33782421, 2021). "In addition, like COL4A5 coding type IV collagen, COL4A3 traditionally causes autosomal dominant Alport syndrome and is reported to change susceptibility to diabetic kidney disease." (PMID 32543079, 2020). "In addition, multiple studies have shown that patients with FSGS were reclassified as Alport syndrome based on mutations found in COL4A3, COL4A4, and COL4A5." (PMID 31921302, 2019). "It will now also be important to establish if the lack of effectivity for Col4a1 renal disease also applies to other kidney pathologies due to mutations in BM components such as Alport syndrome, where PBA reduced ER stress in cells with COL4A5 missense mutations." (PMID 30351356, 2019). "Deletions or pathogenic missense variants in COL4A5 are known to cause X-linked dominant Alport syndrome, however, neither patient exhibits the clinical phenotypes of Alport syndrome." (PMID 30245926, 2018). "The renal manifestations we describe are clinically disparate from Alport syndrome, consistent with an absence of any COL4A5 mutations." (PMID 27811305, 2017). "Most of these deletions involve COL4A5, the major cause of Alport syndrome, yet mutations in COL4A5 do not account for the haematological, dysmorphic and developmental characteristics described in AMME." (PMID 27811305, 2017). "Genetic variants of the COL4A3, COL4A4, and COL4A5 genes encoding α3, α4 and α5 type IV collagen polypeptide chains cause structural alterations of the glomerular basement membrane (GBM) that comprise both Alport Syndrome and Thin GBM Disease." (PMID 27192434, 2016). "The precise prevalence of Alport syndrome in the US is uncertain, but estimates of the prevalence of heterozygous pathogenic variants in these genes are ~1 in 100 individuals for either COL4A3 or COL4A4, and ~1 in 2000 individuals for hemizygous or heterozygous variants in COL4A5." (PMID 40317772, 2025). "In conclusion, we have reported for the first time two cases of X-linked Alport syndrome where the only structure affected by a decrease in COL4A5 immunolabeling was Bowman’s capsule and where neither COL4A3 nor COL4A4 could have thus been at cause." (PMID 38668984, 2024). "For instance, Alport syndrome (AS) is a progressive hereditary renal disease accompanied by sensorineural hearing loss and ocular abnormalities, caused by the pathogenic variants in the genes of COL4A3, COL4A4, and COL4A5 encoding type IV collagen α3, α4, and α5 chains, respectively." (PMID 36685964, 2022). "Alport syndrome has been described as a genetic disorder caused by pathogenic mutations in the collagen type IV alpha 3 (COL4A3), collagen type IV alpha 4 (COL4A4), or collagen type IV alpha 5 (COL4A5) genes encoding type IV collagen α3, α4, or α5 chains, respectively." (PMID 35860818, 2022). "We found there were no clinical features of Alport syndrome not only in six probands with c.2858G>T(p.(G953V)) in COL4A5 plus pathogenic variants in other genes (e.g., WT1, ADCK4, NPHP1, TRPC6, COL4A4, and PAX2) but also in another six probands with only the c.2858G>T(p.(G953V)) variant." (PMID 31576025, 2020). "It provides the disease confirmation or exclusion, identification of atypical Alport syndrome, determination of symptomatic and asymptomatic monoallelic COL4A3, COL4A4, and COL4A5 carriers (especially COL4A5 females), and inheritance pattern establishment." (PMID 40004525, 2025). "Currently, the most accurate method for diagnosing Alport syndrome is comprehensive parallel genetic testing of the entire coding sequences of the COL4A3, COL4A4, and COL4A5 genes using next-generation sequencing (NGS)." (PMID 40004525, 2025).